ENSG00000212490
Synonyms: LOC124900185
Gene: Small nucleolar RNA gene on chromosome 4 (52,748,137 to 52,748,259, forward strand). Ensembl gene ENSG00000212490.
Gene Ontology:
Biological process: RNA processing
Cellular component: nucleolus
Homologues: Paralogues in human: SNORA26 (80% identical).